FOXP3 (forkhead box P3)
Diseases named in the same sentence as FOXP3 in open-access papers (continued):
Sharing a sentence is not in itself a finding about the gene and the disease.
tumor (continued). "PD-L1 co-localisation with CD68 was only associated with high TILs (p < 0.001), whilst with FOXP3, it was associated with smaller tumours (p = 0.028), negative nodal status (p = 0.009) and high sTILs (p = 0.017)." (PMID 34732817, 2021). "Another marker, FoxP3, represents T-regulatory (Treg) cells, the presence of which may inhibit an efficient immune defense against tumor development." (PMID 33712002, 2021). "It is hypothesized that the positive effect of FoxP3+ Tregs may be partially attributed to its ability to suppress inflammatory response, which may promote tumor progression." (PMID 35087741, 2021). "Moreover, 4-NQO induced esophageal carcinogenesis in mice, while silencing of FOXP3 inhibited the tumor growth in EC mice." (PMID 34140005, 2021). "Additionally, FOXP3 was shown to suppress the migration, proliferation as well as invasion of tumor cells in melanoma, breast cancer, glioblastoma as well as ovarian cancer." (PMID 34670484, 2021). "Forkhead box P3 (FOXP3), also known as scurfin, is a transcription factor overexpressed by Tregs and associates with the up-regulation of CTLA-4 expression, which in case of iCC is predictive of tumor recurrence and chemoresistance." (PMID 33922362, 2021). "Foxp3-specific ablation of upstream mTORC1 activators, RagA/B and Rheb, severely impair Treg suppressive function leading not only to uncontrolled systemic inflammation, but also enhanced anti-tumor immunity." (PMID 33868263, 2021). "The tumor microenvironment (TME) in ALK-rearranged caners includes interaction of tumor-associated macrophages (TAMs), CD4+ T cells, CD8+ T cells, regulatory T cells (FOXP3+) and mast cells." (PMID 33806977, 2021). "Immunohistochemistry of the tumor tissue seems to corroborate the Treg hypothesis, showing much higher infiltration of FoxP3+ positive cells to the tumor tissue of S2A treated mice." (PMID 33828163, 2021). "Furthermore, pharmacological inhibition of EGFR signalling led to reduced FoxP3 RNA expression in EGFR expressing tumours of treated mice." (PMID 35052732, 2021). "Therefore, blocking the functional molecules expressed on Tregs such as CTLA-4, PD-1, CCR4, TGF-β, Foxp3, or completely eliminating the presence of Tregs can improve the immune escape effect of tumor inflammatory microenvironment." (PMID 34062992, 2021). "Thus, CD25-targeted NIR-PIT was developed to selectively deplete CD4+CD25+Foxp3+ Tregs in tumor beds to induce the activation of antitumor effector cells." (PMID 34064074, 2021). "Tumour-derived TGFβ induces Foxp3+ Tregs conversion from its CD4+CD25− precursors." (PMID 33941245, 2021). "Foxp3+ T cells were observed in tumor stroma as well as in tumor regions." (PMID 34564709, 2021). "FoxP3+ lymphocytes were the rarest in all locations, demonstrating uniformly low levels in tumour stroma, more variable levels in the tumour nests levels although still relatively low, and predominantly only mild infiltration at the tumour edge." (PMID 32577938, 2020). "Finally, both TH-MYCN and 9464D had similar CD8+:FoxP3+ ratios within the tumor, which were significantly higher than in NXS2 tumors." (PMID 33028899, 2020). "Hence, the depletion of CD4+Foxp3+CD25high Tregs from the peripheral circulation of the patients didn’t increase the efficacy of the DC vaccination against the tumor." (PMID 33519807, 2020). "The same phenomenon was also observed in the K7-derived syngeneic mouse model, as microRNA-200a promoted tumor growth by increasing the percentage of Foxp3+ regulatory T lymphocytes while reducing the proportions of CD4+, CD8+, and IFN-γ+ cytotoxic T lymphocytes." (PMID 31981455, 2020). "In another study, it was demonstrated that most of the intra-tumor CD4+Foxp3+ Treg cells have a Helios+, CTLA-4+, and CD39+ phenotype, but 30% of CD4+Foxp3− cells also expressed markers associated with regulatory functions, including CD25, LAG-3, and latency-associated peptide (LAP)." (PMID 32674255, 2020).
tumor (continued). "Finally, the high infiltration of FOXP3+ TIL and the presence of PD-L1+ immune cells were associated with tumor recurrence in patients with pure DCIS, suggesting a potential benefit in active surveillance or aggressive treatment in such patient groups." (PMID 32216826, 2020). "Data from IPEX patients with impaired isoform ratios indicate that modulated FOXP3 splicing could enhance T-cell responses via exon 7 exclusion (e.g., in tumor-specific T cells) or promote immunosuppression via exon 2 inclusion (e.g., in immunopathology)." (PMID 33194927, 2020). "Also, the expression of FOXP3 in tumor cells was extremely statistically significant when correlated with a mitotic index (t test, two-tailed P value < 0.0001)." (PMID 33274240, 2020). "In line with this notion, analysis of FOXP3+ CD4+ T cell frequencies across the tissues of MC38 tumor‐bearing wild‐type and Usp44fl/flFoxp3Cre+ mice revealed marked reductions in the relative size of the Treg pool when USP44 expression was lacking in these cells." (PMID 32644293, 2020). "Thus, some BM resected under ipilimumab therapy showed dense infiltration of CD8+ cytotoxic tumor infiltrating lymphocytes (TILs) and FoxP3+ regulatory T cells, indicating a triggered immune response under therapy." (PMID 32117271, 2020). "Thus, the presence of FoxP3+ T-cells in the tumor microenvironment would indicate an unfavorable prognosis." (PMID 32785290, 2020). "More tumor-infiltrating Foxp3+ Tregs expressed Tbet in ALK5ΔFoxp3 mice compared to littermate control (LM), suggesting a more suppressive regulatory T cell phenotype in ALK5ΔFoxp3 mice may be contributing to the more rapid tumor growth." (PMID 32273499, 2020). "The overexpression of FOXP3 significantly reduced tumor cell proliferation, migration and invasion." (PMID 33116119, 2020). "We found that FOXP3+ Tregs infiltrated into the tumor microenvironment." (PMID 31970893, 2020). "Therefore, it is crucial to assess heterogeneity of FOXP3+ T cells in tumor tissues in order to evaluate their contribution to anti-tumor immune response." (PMID 32580514, 2020). "Moreover, by using immunohistochemical staining, we revealed that the number of FOXP3-positive cells in the tumor tissues were similar between the RFA and the control group." (PMID 32719347, 2020). "Expression of FOXP3 and TdT in cancer cells suggests that T cells may play a part in tumor immune escape." (PMID 32993581, 2020). "The ICOS-driven interaction between tumor associated CD4+ T cells and ICOSL-expressing TA-pDCs sustain the expansion of ICOS+ FoxP3+ Tregs in the tumor microenvironment and promote the secretion of IL-10 and TGF-β from Tregs, which support an immunosuppressive microenvironment and tumor progression." (PMID 32054102, 2020). "Moreover, the neoantigen-pulsed DC vaccine groups had more CD8+ T cells and fewer Foxp3+ T cells infiltrating into the tumor microenvironment." (PMID 31807878, 2020). "Although low in numbers, Foxp3+ Treg cells remained functional in NARA1leukin-treated animals; thus, the depletion of Treg cells in Foxp3DTR mice by using diphtheria toxin synergized with NARA1leukin therapy to further improve tumor control." (PMID 33353953, 2020). "The results show the FOXp3 signal in the tumor mass as strong in the control animals, which may indicate a strong immunosuppressive Treg effect, which may be mitigated by administering the combined treatment." (PMID 32469935, 2020). "Treg-selective deletion of essential Treg factors such as Neuropilin-1 (Nrp-1), suppressor of cytokine signaling 1 (SOCS1), enhancer of zeste homolog 2 (EZH2), Eos (IKzf4), or CARMA1 leads to Foxp3 downregulation and inflammatory cytokine secretion, conferring resistance to tumor growth in the host." (PMID 33024109, 2020). "Additionally, we also report quantity of FOXP3 expressing lymphocytes in tumor microenvironment and its correlation with VDR expression." (PMID 32513132, 2020).
tumor (continued). "In addition, tumor-associated immune response (CD3, p = 0.04; CD45ro, p = 0.03; FoxP3, p = 0.05)) and frontal tumor location (p = 0.01) were associated with longer overall survival (OS) in female patients." (PMID 32560244, 2020). "Although the total number of CD8+ FOXP3+ cells is small, they could play an important role in the tumour microenvironment (TME)." (PMID 33276543, 2020). "Interestingly, in PTC, IDO expression showed a significant correlation with FoxP3, which suppressed the immune microenvironment by inducing the regulation of the FoxP3 phenotype to promote tumor escape." (PMID 32626535, 2020). "Tumor-Evoked Regulatory B Cells (tBreg) exert antitumor activity by promoting conversion of the resting CD4+ T cell into FoxP3+ Treg by secretion of TGF-β then the Treg inhibit T cell proliferation and promote tumor metastasis by suppression of the anti-tumor effects of CD8+ T cells and NK cells." (PMID 32664587, 2020). "Also, FOXP3 expression in tumor cells correlated, in our study, with the mitotic index, sustaining the previously known fact that FOXP3 is implicated in tumor progression, mitotic actively tumors being mostly positive for FOXP3." (PMID 33274240, 2020). "Increased CD4+FOXP3+ T‐cell density in the GC tumor correlated with prolonged survival." (PMID 32377339, 2020). "However, treatment significantly reduced activated Tregs in the tumor microenvironment: Foxp3+CTLA4+ CD4+ Tregs were reduced in all patients, from 11.8% to 2.9%, p = 0.0067." (PMID 32681091, 2020). "Indeed, the up-regulation of Foxp3 was correlated with the p16INK4a expression, an important protein for the HPV integration and was associated with the tumor growth." (PMID 32957741, 2020). "Indeed, our results revealed that most tumor samples scored as FoxP3-positive in interstitial lymphocytes (74%), suggesting Treg tumor infiltration, and strongly correlated with interstitial CTLA-4 expression." (PMID 32123292, 2020). "Its receptor, VEGFR2, is expressed selectively in intra-tumor Treg cells with high expression of Foxp3, and it is proposed that both VEGFR2 and Foxp3 may be better predictive markers for recurrence and survival in patients with CRC." (PMID 32674255, 2020). "Furthermore, there was a significant positive correlation between tumor stromal infiltration by FOXP3+ T-regulatory cells and local infiltration of the other immune cell types investigated." (PMID 32316975, 2020). "The poor tumor growth and robust anti‐tumor immune mobilization seen in Usp44fl/fl Foxp3Cre+ mice illustrate how FOXP3‐stabilizing DUBs like USP44 may be tempting molecular targets for such future therapy." (PMID 32644293, 2020). "Ablation of Foxp3+ Tregs significantly delayed tumour development." (PMID 32680511, 2020). "Chemotactic factors, cell metabolism, oxidative stress, and pH in the tumor microenvironment could affect FOXP3+ Treg infiltration in cancer tissues." (PMID 33062072, 2020). "HCC tumor tissues usually contain the abundance of infiltrated lymphocytes that can express FOXP3." (PMID 33116119, 2020). "Although we found an association of poor outcome of low FoxP3 with LR in luminal tumours, this was not significant in MVA." (PMID 32825588, 2020). "Besides, at later stages of tumor development a FOXP3+ TGFβ+ CD25+ CD127− CD8+ T cell population is expanded." (PMID 33076479, 2020). "In addition, our results suggest that CTLA-4+ cells suppress the function of FoxP3+ T-cells and promote anti‐tumor immunity in OSCC." (PMID 32785290, 2020). "However, high glycolysis group was associated with lower infiltration of tumor-killing immune cells such as NKT cells and higher immune checkpoints expression such as PD-L1, CTLA4, FOXP3 and IDO1." (PMID 32070368, 2020).
tumor (continued). "The number of tumor-infiltrating FOXP3+ T cells ranged from 0 to 30 under the high-power field." (PMID 32216826, 2020). "Moreover, Treg depletion using DEREG (Foxp3-DTR-GFP) mice triggered total tumor rejection of either shCtrl or shSK1 Yumm tumors, demonstrating that Treg are a major immunosuppressive population." (PMID 31974367, 2020). "Here, we analysed whether HHLA2 expression levels correlated with numbers of tumour-infiltrating CD8+ or Foxp3+ T cells." (PMID 32071413, 2020). "CD4+CD25+FoxP3+ cells isolated from patients diagnosed with HCC showed an increased transcriptional activity compared to controls, regardless the pathogenic basis of tumor development." (PMID 32488850, 2020). "Solanine may enhance the antitumor immune response by downregulating the proportion of CD4+CD25+ Treg and the expression of Foxp3 and TGFβ in tumor tissues." (PMID 33204731, 2020). "Concerning the CTLA-4 and FoxP3 expression, although detected in both interstitial lymphocytes and tumor cells, a positive association was found only between interstitial CTLA-4 and FoxP3 expressions (R = 0.387, P = 0.01), which is negatively associated with the serum CTLA-4 levels (P = 0.03)." (PMID 32123292, 2020). "Interestingly, depleting the Ly6G+ also reduced the number of CD4+-FoxP3+ cells in the tumor site, suggesting an alteration of tumor microenvironment upon depletion of LY6G+ cells." (PMID 32182988, 2020). "Here, our data showed that hepatocytes could express FOXP3 and its isoforms but only full-length FOXP3 functioned as a tumor suppressor in HCC." (PMID 33116119, 2020). "In our experience, TME changed towards a more inflamed environment, evidenced by the increase of cytokines like CXCL10 and CCL2, and the decrease of immunosuppressive molecules (like FoxP3 and Nos2), and molecules that promote tumor growth and invasiveness (like IL10 and TGFβ)." (PMID 32064039, 2020). "EZH2 inhibition destabilizes Foxp3 expression and inhibits tumor growth in vivo." (PMID 32849557, 2020). "In histopathology, FOXP3 remains the primary marker for detection of Treg in fixed tumor tissues." (PMID 33013886, 2020). "Moreover, CD4+CD25+FoxP3+ Treg cells are capable of suppressing Th1 or Cytotoxic T lymphocytes responses and represent a major mechanism of tumor escape in several cancers." (PMID 33100273, 2020). "However, a high density of Foxp3+ TILs in the tumour stroma indicated a worse relapse/recurrence-free survival (HR = 1.90, 1.05–2.76) in NSCLC." (PMID 33170901, 2020). "The in vivo mouse tumor model study confirmed the inhibitory effect of FOXP3." (PMID 33116119, 2020). "This fact raises the question of whether the invasion of TDLNs during tumor spreading produces an accumulation of immunosuppressive cells—like FOXP3+ CD4+ regulatory T cells (Tregs)—and imparts a tolerogenic microenvironment." (PMID 32601304, 2020). "The increased infiltration of immunosuppressive CD163+ macrophages, and increased infiltration of regulatory FOXP3+ T cells l, has been shown to favour tumour growth, in contrast to the presence of tumour infilitrating lymphocytes (TILs) which is positively correlated with survival." (PMID 32560564, 2020). "Furthermore, many tumor cells release cytokines, chemokines, and growth factors that recruit and induce FOXP3+ Tregs, and induce MDSCs and macrophages to release Th2 cytokines such as Tgf-β, IL-4, IL-10, and IL-13 which suppress anti-tumor immunity." (PMID 32508830, 2020). "In addition, tumor-draining lymph nodes in the Nur77/Nurr1-double knockout mice show downregulation of Foxp3+ Tregs and an accumulation of CD8+ T cells with higher expression of Ki-67 compared to the wild-type mice." (PMID 33086676, 2020). "Based on our results, FOXP3+ tumor infiltrating lymphocytes in OSCC may have a similar inhibitory effect as other solid tumors by inhibiting the cytotoxic activity of CD8+ T cells and affecting the response to immunotherapy." (PMID 33364188, 2020).
tumor (continued). "Assessing cytotoxic CD8+ T cells and regulatory Foxp3 T cells together, as the two major components of the tumour-related immune system, could provide more precise estimates of their effects on HPSCC patient survival." (PMID 32758195, 2020). "In the immunosuppressive TME, particularly in T-cell inflamed tumours, several types of tumour-promoting cells are present, such as CD4+ regulatory FoxP3+ T-cells, tumour-associated macrophages, myeloid-derived suppressor cells, and infiltrating cytotoxic CD8+ T-cells." (PMID 33121210, 2020). "In addition, when both CD8+ T cells and FOXP3+ T cells are present in a tumor, they are spatially very close." (PMID 33117345, 2020). "While NK cells, CD4+ and CD8+ T cells, dendritic cells (DC) and pro-inflammatory M1 macrophages promote anti-tumor immune responses, heterogeneous populations of myeloid-derived suppressor cells (MDSC), FOXP3+ regulatory T cells and M2 macrophages counteract tumor immunity." (PMID 32987799, 2020). "Foxp3+ T regulatory cells (Tregs), B220+CD3 B cells, MHC-IICD64+ myeloid cells (putative monocyte-derived tumor-associated macrophages [TAMs]), CD11cSIRPa+MHC-II+ myeloid cells (putative activated macrophages [aMacs]), CD11c+MHC-II+ DCs, and MHC-II+ SIRPaDIM myeloid cells." (PMID 32320656, 2020). "FOXP3, an important marker in Treg cells, can inhibit cytotoxic T cells from attacking tumor cells." (PMID 33247170, 2020). "Patient distribution according to locations and densities of tumor-infiltrating FoxP3+ T-cells." (PMID 32785290, 2020). "Our bioinformatic analysis showed that FOXP3 was correlated with many significantly altered immune related genes, indicating that FOXP3 might be an important TF for regulating the immune tumor microenvironment of HNSCC." (PMID 33224866, 2020). "Furthermore, a significant increase in the ratio of GzmB+CD4+Foxp3− to CD4+ Foxp3+ cells was also observed post-treatment, suggesting an inverse relationship between Treg cell frequency and GzmB expression in tumor-infiltrating CD4+ T cells." (PMID 31924474, 2020). "Furthermore, the number of tumor-infiltrating Foxp3+ Treg in tumor tissue increases with the progression of tumor stage." (PMID 32707869, 2020). "Our results also indicate that FoxP3+ T-cells may exert site-specific anti-tumor effects in patients with OSCC." (PMID 32785290, 2020). "Conversely, the number of suppressive CD25+ and FOXP3+ double-positive Tregs significantly decreased in the tumor tissues from the NDV-MIP3α-injected mice, about onefold compared with the NDV-WT-injected mice and about threefold compared with the PBS-injected mice." (PMID 32759233, 2020). "Our results suggest that the EVs secreted by genetically modified tumor cells harboring TNFSF ligands can induce T cell proliferation, inhibit the transcription factor FoxP3, associated with the maintenance of Treg phenotype, and enhance antitumor activity mediated by immune cells." (PMID 32939048, 2020). "Nonetheless, CD4+CD25+FOXP3+ T cells remains the central focus of Treg-based research in cancer biology due to their potent immunosuppressive functions and their presence in a wide range of tumor types." (PMID 33013886, 2020). "A separate preclinical study also observed the enhanced antitumor immune response with significantly decreased FoxP3+ expression in circulating Tregs and increased tumor-infiltrating G-MDSCs in syngeneic mouse cancer models under entinostat and anti-PD-1 antibody treatment." (PMID 32158754, 2020). "Importantly, combination ROCKi+anti-PD-1 induced more tumor regressions and reduced numbers of FOXP3+ Tregs." (PMID 32391428, 2020). "The anti-interleukin-10 (IL-10) antibody partially blocked this increase, suggesting that TAMs may trigger an increase in the population of FoxP3+ Treg cells in the tumor, thereby promoting the progression of HCC." (PMID 31464625, 2019).